LINC00629 (long independently transcribed non-coding RNA 629)
Synonyms: LINC00629A; LINC00629B; LINC00629C; LINC00629D
Gene: Long non-coding RNA gene on chromosome X (134,549,747 to 134,560,401, forward strand). Ensembl gene ENSG00000227060.
Diseases named in the same sentence as LINC00629 in open-access papers:
LINC00629 is named in the same sentence as 4 diseases in open-access papers, as found by Europe PMC text mining. Sharing a sentence is not in itself a finding about the gene and the disease. The quoted sentences say what the papers report.
osteosarcoma (2 papers, 2022 to 2023). A usually aggressive malignant bone-forming mesenchymal neoplasm, predominantly affecting adolescents and young adults. "Collectively, our findings highlight the role of NUCKS1 in regulating asparagine metabolism and reveal that LINC00629 is an important regulator of NUCKS1 that contributes to NUCKS1 upregulation in osteosarcoma." (PMID 37528150, 2023). "Recently, we uncovered the role of LINC00629 in osteosarcoma and identified differentially expressed proteins in MNNG/HOS cells with or without LINC00629 knockdown using label-free quantitative proteomics." (PMID 37528150, 2023). "Taken together, our findings highlight the role of NUCKS1 in regulating asparagine metabolism and reveal that LINC00629 is an important regulator of NUCKS1 that contributes to NUCKS1 upregulation in osteosarcoma." (PMID 37528150, 2023). "To better understand the function of LINC00629 in osteosarcoma cell, we then determined the effects of LINC00629 on tumour growth and metastasis in vivo." (PMID 36539799, 2022). "Collectively, our data indicate that LINC00629 is a critical long noncoding RNA (lncRNA) induced by ER stress and plays an oncogenic role in osteosarcoma cell by activating the KLF4-LAMA4 axis." (PMID 36539799, 2022). "Therefore, our results uncover a novel role of NUCKS1 in regulating asparagine metabolism and identify LINC00629 as an important regulator of NUCKS1 upregulation in osteosarcoma." (PMID 37528150, 2023). "To determine whether LINC00629 elevates the osteosarcoma cell adaption to ER stress and facilitates tumorigenesis by regulating the KLF4-LAMA4 axis, we first overexpressed LINC00629 in KLF4- or LAMA4-depleted MNNG/HOS cells and these cells were treated with 3 μM TM for 36 h." (PMID 36539799, 2022). "Collectively, our data indicate that LINC00629 acts as a miR-4768-3p sponge and promotes NUCKS1 expression in osteosarcoma cells." (PMID 37528150, 2023). "Collectively, these results revel that LINC00629 promotes NUCKS1 and ASNS expression in osteosarcoma cells." (PMID 37528150, 2023).
choriocarcinoma (1 paper, 2016). An aggressive malignant tumor arising from trophoblastic cells. "Based on their expression profile and their effects on migration and invasion in a model of choriocarcinoma, our study suggests a potential role for MIR503HG and LINC00629 genes in tumorigenesis and human reproduction, considering the similarity among normal placenta and germinal tissues to tumors." (PMID 27023770, 2016).
tumor (2 papers, 2022). "In accordance with previous evidence, we found that LINC00629, as a tumor suppressor, promoted apigenin-induced apoptosis in OSCC." (PMID 36445338, 2022). "Compared with the control group, knockdown of LINC00629 significantly suppressed tumour formation, as indicated by reduced tumour weights and tumour sizes." (PMID 36539799, 2022). "Collectively, these results suggest that LINC00629 depends on the KLF4-LAMA4 axis to elevate the adaption to ER stress and promote tumour growth and metastasis in MNNG/HOS and 143B cells." (PMID 36539799, 2022).
cancer (1 paper, 2016). A tumor composed of atypical neoplastic, often pleomorphic cells that invade other tissues. "MIR503HG and LINC00629 genes are located in the same region as PLAC1, whose expression is restricted to placenta and recently was found to be expressed in cancer cells." (PMID 27023770, 2016).